CD44 (CD44 molecule (IN blood group))
Diseases named in the same sentence as CD44 in open-access papers (continued):
Sharing a sentence is not in itself a finding about the gene and the disease.
tumor (continued). "The IC50 values of Juglone for inhibiting cell growth were 1.38 μM for CD44+CD133+ tumor-initiating Caco-2 cells and 1.21 μM for ΔCD44+CD133+ non-tumor-initiating Caco-2 cells, suggesting Juglone is a small-molecule compound targeting CD44+CD133+ cells to inhibit their tumorigenic tendency." (PMID 35433695, 2022). "We compared mass spectrometry proteomic profiling of clustering and non-clustering TNBC patient-derived xenografts (PDXs) tumor cells and identified CD81, a tetraspanin protein enriched in extracellular vesicles (EVs), as one of the altered proteins upon CD44 depletion." (PMID 36193887, 2022). "Furthermore, we found that as few as ten ALDH+CD44+CXCR4+CD24+-PCa cells, but not other subsets, could develop a palpable tumour within 100 days of implantation." (PMID 34247196, 2021). "A lack of published research directly comparing the ALDH+ and CD44+/CD24- breast CSC populations in the context of patient tumor samples indicates an opportunity for further study to elucidate the mechanism of prostaglandin signaling in breast CSCs and the tumor microenvironment." (PMID 35127497, 2021). "However, these tumor-infiltrating CD8+ T lymphocytes exhibited a highly activated phenotype (upregulated CD25, CD44, and CD69 and down-regulated CD62L expression) but lacked effector cell function, measured by a killing assay, suggesting modulation of the CD8+ T lymphocytes by the tumor environment." (PMID 32733446, 2020). "In addition to the presence of CD44 and lack of ALDH, mesenchymal‐like CSCs occupy a peri‐stromal location, whereas ALDH+/CD44− epithelial‐like CSCs are located more centrally within the tumour." (PMID 31591823, 2020). "They found a large-sized and non-dividing CD44+ ALDH1+MYD88+ subtype of OCs, which exhibits several properties of CSCs, including the capacity to generate tumors in immunodeficient mice, the capacity of functioning as tumor vascular progenitors, and chemoresistance." (PMID 32899775, 2020). "Targeting resistant clones and cancer stem cells is a challenging task, as CSC markers (including CD133, CD44, and ALDH) are not exclusively expressed by these cells’ sub-populations, and wide phenotype variability exists among CSCs from different patients and also within the same tumor." (PMID 31480477, 2019). "These cells were phenotypically CD44+CD24−/low and as few as 100 cells were capable of forming tumours, in contrast to the tens of thousands of cells with other phenotypes that could not reform tumours in mice." (PMID 29991569, 2018). "A mouse xenograft model of transformed mammary epithelial cells revealed that i.p.-applied MTF targets the CD44 high and CD24 low expressing CSC population and when combined with the anthracycline compound doxorubicin, known to target non-cancer stem cells, synergistically inhibits tumor growth." (PMID 30241339, 2018). "Although pan-cytokeratin and CD44 did not reveal any SUM159 cells in the bone, these results do not rule out the possibility that the tumor burden was below the level of detection by immunostaining, particularly since we detected tumor cells by flow cytometry in 100% of SUM159-inoculated mice." (PMID 30250146, 2018). "Thus, the CD44+/24–/low population abundance could be independent of BRCA1 expression and dependent on the tumor sub-type." (PMID 27229859, 2016). "Indeed, treatment with T-DM1 not only depleted pre-existing CD44+/CD24−/low cells at concentrations that failed to affect the bulk of tumor cells, but also prevented the EMT-mediated induction of CSC-like properties in differentiated tumor cells." (PMID 26474458, 2015). "Notably, CD44+CD24low+ cells preferentially express ES genes and metastatic gene signatures, show greater motility and invasion, and in the MDA-MB-231 model, yield tumours that metastasize while CD44+CD24neg did not." (PMID 23982961, 2013).
tumor (continued). "To test whether culturing tumor cells in non-adherent condition could affect methylation of the genes analyzed, we also subjected sorted subpopulations of SUM159 cells (ALDH+, ALDH-, CD44+CD24-, CD44+CD24+) to gene methylation analysis." (PMID 23883436, 2013). "Interestingly, although ER expression was observed in 50 of the 121 (41.3%) patients with CD44/CD24 data, the presence of CD44+/CD24- tumor cells was not significantly correlated with positive ER expression in all patients and in patients with recurrence or metastasis." (PMID 22762532, 2012). "Similarly, CD44 splice isoform switching from CD44v to CD44s was essential for EMT and tumor metastasis, while the interaction of phosphorylated cortactin with CD44s but not CD44v induced the activation of invadopodia driving tumor cell invasion and metastasis." (PMID 40542654, 2025). "Since CD44- Epi_C1 clusters were located closer to the interior of the tumor, away from infiltrated immune cells and stromal cells, compared to CD44+ Epi_C1 clusters, we speculated that PTN from CD44- Epi_C1 may interact with other cell clusters rather than TANs or CAFs at the tumor leading edge." (PMID 40069574, 2025). "In addition, immunofluorescence and immunoblot analyses showed that a CSC marker, CD44, was strongly expressed in tumor tissues of MKN28 controls but not in MKN28 viperin-KD cells, and viperin expression was detected in both CD44+ CSCs and CD44– non-CSCs in tumor tissues of MKN28 controls." (PMID 36227691, 2022). "Furthermore, the method for identification of CD44-/CD24- TNBC cells did not include a positive tumor molecular marker, which might contaminate some other types of cells, although using histological tissue sections for identification of tumor cells." (PMID 34318746, 2021). "For instance, in the HER2-OE cell line SK-BR-3, the CD44/CD24 ratio was low, whereas the expression level of ALDH1 was high, suggesting that single CSC marker alone might not be enough to characterize tumor stemness or to evaluate tumor malignancy and prognosis." (PMID 29062075, 2017). "Retention of CD44+CD24- phenotype during in vitro and in vivo passages suggest that CD44+CD24-Sca1+ cells may be a highly tumorigeneic phenotype within the primary tumor cells which have characteristics similar to stem-like cells, but they may not be tumor initiating cells." (PMID 24324806, 2013).
cancer (4,389 papers, 1995 to 2026). A tumor composed of atypical neoplastic, often pleomorphic cells that invade other tissues. "KEGG pathway enrichment revealed upregulation of focal adhesion and proteoglycans in cancer pathways—the latter featuring CD44 as a key molecule involved in MASLD-associated metastases." (PMID 41545340, 2026). "ALDH1 and CD44 were expressed in 13 of the 16 identified cancer stem cell phenotypes and have previously been linked to patient outcome, implying a relevance to cancer in general." (PMID 39888143, 2025). "Xanthine dehydrogenase, a rate-limiting enzyme involved in purine metabolism, was associated with the expression of cancer stem biomarkers, such as CD44 or CD133 in HCC." (PMID 40311679, 2025). "Further western blotting analysis manifested that E2F1 deficiency reduced the expression of OCT4 and CD44, which are key regulators of cancer stemness, in Huh-7 and Hep3B cells." (PMID 40221814, 2025). "Beyond GBM, CD44 has been implicated in aggressive behavior and tumorigenicity in multiple cancer types, such as breast, kidney, pancreatic, prostate, and gastrointestinal cancers." (PMID 39977830, 2025). "The epithelial markers included epithelial specific antigen (ESA; also known as EPCAM) and CD44, a glycoprotein involved in cell adhesion, migration, and commonly associated with cancer stemness (Baeuerle and Gires, 2007; Zöller, 2011)." (PMID 40755138, 2025). "CD44 and its variant isoforms play a significant role in cancer progression and MDR across various cancer types." (PMID 40363706, 2025). "CD44, a cell surface glycoprotein, is implicated in various physiological and pathological processes, including cancer progression and metastasis, making it an attractive therapeutic and diagnostic target." (PMID 40001633, 2025). "Despite extensive research on the role of miR-216a-5p in PDAC and other types of cancer, its potential connection with PaCSCs and their associated markers CD44/CD24/CxCR4 and ALDH1 remains unexplored." (PMID 40243417, 2025). "These interactions underline the complexity of CD44’s functions responsible for cancer progression and resistance to treatment." (PMID 40114966, 2025). "Through the manipulation of the signaling pathways linked to CD44 expression, these nanocarriers have the potential to hinder the aggressive activity of cancer cells, therefore inhibiting their capacity to multiply and move." (PMID 41367861, 2025). "CD44, a cell surface glycoprotein, has been implicated in oncogenesis across multiple cancer types and has been associated with the advancement and metastasis of OS." (PMID 40531089, 2025). "Through a chondroitin sulphate-mediated association with CD44, secreted MM Serglycin seems to be capable of exerting a direct control of cancer cell growth within the bone-marrow environment." (PMID 39980017, 2025). "Addressing MDR requires a deeper understanding of the molecular mechanisms underlying resistance, particularly those involving cancer stem cells (CSCs) and their associated markers, such as cluster of differentiation 44 (CD44) variants." (PMID 40363706, 2025). "Suppression of de novo lipogenesis via FA synthase (FASN) inhibition was shown to attenuate CD44 expression, possibly through its palmitoylation, highlighting the association between lipid metabolism and cancer stemness." (PMID 40882371, 2025). "In the murine 4T1 model, both CD44+CD24− and CD44+CD24+ populations have been positively associated with cancer-initiation potential, illustrating model-specific variability in CD24’s function." (PMID 40783744, 2025). "CD44 is a well-known marker for cancer stem cells and has been associated with poor prognosis and treatment resistance in OSCC." (PMID 40906645, 2025). "In conclusion, CD44 and its variants represent a promising target for a wide range of diseases of the CNS, including (auto)inflammatory diseases, cancer, and neurodegenerative diseases." (PMID 40943148, 2025).
cancer (continued). "In hematological and epithelial tumors, the hyaluronate receptor CD44, a class I membrane glycoprotein, is overexpressed and is associated with metastases and poor prognosis in many forms of cancers." (PMID 40646591, 2025). "High HO-1 expression is linked to stem-cell-like properties in various cancers, and HO-1 inhibition reduces expression of CD44, a stemness marker." (PMID 40864800, 2025). "Overall, the cancers analyzed exhibit distinct expression profiles of CD44 isoforms/variant exons, based on our findings and immunohistochemical data available in the literature." (PMID 40114966, 2025). "In OC, IL6 via STAT3 promotes the expression of CD44, a transmembrane glycoprotein associated with cancer cell stemness." (PMID 40427188, 2025). "CD44 also facilitates lymphocyte infiltration, macrophage polarization, and the differentiation of mesenchymal stem cells (MSCs) into cancer-associated fibroblasts (CAFs)." (PMID 40524208, 2025). "GSH biosynthesis is enhanced in cancer cells that express the variant isoform of the surface antigen CD44 (CD44v), which is overexpressed in certain types of cancer." (PMID 40362369, 2025). "CD44 variant isoforms, particularly CD44v8-10, are established cancer stem cell markers in human gastric cancer and are associated with chemotherapy resistance and metastatic potential." (PMID 40673273, 2025). "We determined the moderately positive statistically significant association between the cancer grade and CD44 (r = 0.3930, p < 0.0001), VDR (r = 0.4170, p < 0.0001), and FIGO stage (0.3875, p < 0.0001)." (PMID 40332380, 2025). "Therapeutic approaches targeting CD44 cleavage and its associated pathways are emerging as promising strategies in cancer treatment." (PMID 41440277, 2025). "This study elucidated the molecular mechanism underlying CD44 upregulation during collective migration of luminal-type BrCa cells, providing potential therapeutic targets to prevent cancer metastasis." (PMID 40409554, 2025). "Another important factor associated with cancer stemness and cancer development/metastasis is CD44, including both its standard (CD44s) and variant (CD44v) forms." (PMID 40182121, 2025). "Collectively, the diversity of CD44 isoforms underlies their specialized roles in processes such as immune cell homing, epithelial differentiation, tissue remodeling, and cancer progression." (PMID 41009438, 2025). "We also detected in CIN + PDOs enhanced expression of CD44 gene, encoding a cell-surface receptor that plays a role in cell–cell interactions, cell adhesion and migration, which is increased in cancer cells with an EMT stem cell-like phenotype." (PMID 40022181, 2025). "xCT is stabilized at the cell surface by a variant isoform of CD44 (CD44v), and CD44v-positive cancer cells show enhanced intracellular GSH biosynthesis." (PMID 40362369, 2025). "In TNBC, tumors with high PD-L1 expression are associated with enhanced immune and cancer stemness pathways, further elucidating their connection to CD44." (PMID 39977830, 2025). "Although various splicing variants of CD44 are expressed on the cell membrane of cancer cells, the hyaluronic acid binding domain (HABD) is highly conserved among the CD44 splicing variants." (PMID 40001633, 2025). "The second plasma membrane receptor examined here is CD44, due to its association with cancer stem cell characteristics." (PMID 40221767, 2025). "Recombinant neprilysin and ECE1 inhibition led to decreased protein levels of vimentin and CD44, which are also associated to acquired stemness traits in several types of cancer." (PMID 40830989, 2025). "CD44, a transmembrane glycoprotein, and its splice variants (CD44v) mediate cell adhesion, migration, and survival, contributing to cancer stem cell (CSC) maintenance and therapy resistance." (PMID 40363706, 2025). "CD44 variant (CD44v) isoforms are involved in promoting cancer metastasis, sustaining cancer stem cell (CSC) properties, and conferring resistance to therapeutic interventions." (PMID 41369362, 2025).
cancer (continued). "The association of CD44 variant/only constant exon expression levels with clinical outcomes of cancer patients." (PMID 40114966, 2025). "Studies have identified the surface adhesion molecule CD44 as a marker of gastric CSCs implicated in cancer progression." (PMID 40864800, 2025). "Further, ligand–receptor interactions differed: never‐smokers exhibited CD27+ B cell interactions via LGALS9–HAVCR2/CD44/CD45 and ANXA1–FPR1/FPR2, whereas smokers utilized CD74‐CXCR4/CD44 pathways linked to cancer progression." (PMID 41377765, 2025). "By facilitating PTBP1-mediated alternative splicing of CD44 mRNA, CTC-490G23.2 upregulates the expression of CD44 variant isoform CD44v, which promotes cancer metastasis." (PMID 39937018, 2025). "Insight on the expression profile of different splice variants of CD44 can be of use for better understanding of cancer-specific molecular fingerprints and choosing an optimal cancer targeting strategy." (PMID 40114966, 2025). "An interesting hallmark of cancer is the role of CD44 in the epithelial‐to‐mesenchymal transition (EMT)." (PMID 40538061, 2025). "Particularly, CD44 variant isoforms (CD44v), often upregulated in malignant cells, endow cancer-initiating cells such as self-renewal, niche preparation, epithelial–mesenchymal transition, and resistance to apoptosis." (PMID 40805206, 2025). "Research has established that higher stemness in cancer is linked to greater malignancy and chemotherapy resistance, with CD44 serving as a key marker for cancer stem cells." (PMID 40849307, 2025). "CD44+ cells that are deficient in autophagy exhibit decreased levels of reactive oxygen species and boost cancer stemness through the activation of NRF2 signalling." (PMID 40665579, 2025). "CD44 has been implicated as a cancer stem cell marker in several malignancies of hematopoietic and epithelial origin." (PMID 40868982, 2025). "Given the importance of CD44 as a cancer biomarker, several review articles explore the diagnostic and therapeutic value of cell-surface CD44." (PMID 41440277, 2025). "CD44 is also implicated in epithelial-to-mesenchymal transition and serves as a biomarker of poor prognosis in various cancer entities." (PMID 40395327, 2025). "Several CD44 variants, which are generated by alternative splicing, have been shown to be involved in cancer metastasis." (PMID 39580584, 2025). "We subsequently explored marker genes linked to the biological behaviour of cancer cells, identifying the enrichment of eight marker genes in CD44+ malignant cell clusters." (PMID 38982317, 2024). "For exploring the CD44 molecular mechanisms affecting cancer occurrence biological processes, we performed pathway enrichment analysis on CD44 and its associated genes." (PMID 38590654, 2024). "CD44 has been widely implicated as a marker of cancer stem cells in multiple cancer types including OPC." (PMID 39328208, 2024). "Herein, we discuss the present understanding of the functional and structural roles of CD44 in the pathogenic mechanism of multiple cancers." (PMID 38783892, 2024). "This study supports the feasibility of a CD44-based oral rinse test as an affordable and convenient adjunctive tool for early detection of aerodigestive tract and other cancers in high-risk populations." (PMID 39030509, 2024). "Because CD44 is known as a cancer stem cell (CSC) marker and CSCs are deeply associated with chemoresistance of various human malignancies." (PMID 39518040, 2024). "Metavert treatment of human organoids also strongly downregulated mRNA and protein levels of the cancer stem cell markers CD44 and SOX2 associated with EMT and chemotherapy resistance." (PMID 39217851, 2024). "As previously noted, CD44 has been associated with chemo resistance in different types of cancer, including CRC." (PMID 38391955, 2024). "In the mass, the main mutation type of CD44 in pan-cancer was amplification, and the overall genome alternation rate of CD44 in pan-cancer was 2.2%." (PMID 38590654, 2024).